CSTL1 (cystatin like 1)
Synonyms: dJ322G13.4; CTES1; RCET11
Tractability: Antibody: UniProt places it where antibodies can reach, with high confidence; UniProt predicts a signal peptide or a membrane-spanning region; its Gene Ontology location is reachable by antibodies, with medium confidence.
Gene: Protein-coding gene on chromosome 20 (23,426,104 to 23,444,930, forward strand). Ensembl gene ENSG00000125823.
Subcellular location: Secreted
Gene Ontology:
Molecular function: cysteine-type peptidase activity; cysteine-type endopeptidase inhibitor activity
Biological process: signaling receptor ligand precursor processing
Cellular component: extracellular region
Genetic constraint (gnomAD): Loss-of-function variants: 7 observed, 8.4 expected, observed/expected ratio (o/e) 0.83, 90% interval 0.47 to 1.54. That is too few expected variants to judge how well the gene tolerates losing a copy. Missense variants: 130 observed, 138.73 expected, observed/expected ratio (o/e) 0.94, 90% interval 0.81 to 1.08. Synonymous variants: 59 observed, 57.76 expected, observed/expected ratio (o/e) 1.02, 90% interval 0.83 to 1.27.
Homologues: Orthologues: chimpanzee CSTL1 (97% identical), macaque CSTL1 (90% identical), rabbit CSTL1 (77% identical), dog CSTL1 (70% identical), mouse Cstl1 (66% identical), pig CSTL1 (66% identical), guinea pig CSTL1 (66% identical), rat Cstl1 (65% identical), Caenorhabditis elegans cpi-2 (15% identical), zebrafish si:busm1-57f23.1 (15% identical), Caenorhabditis elegans cpi-1 (14% identical), Caenorhabditis elegans K08B4.7 (4% identical). Paralogues in human: CST8 (27% identical), CST1 (26% identical), CST11 (26% identical), CST2 (26% identical), CST3 (26% identical), CST4 (26% identical), CST6 (25% identical), CST5 (24% identical), CST7 (24% identical), CST9L (21% identical), CST9 (15% identical).
Diseases named in the same sentence as CSTL1 in open-access papers:
CSTL1 is named in the same sentence as 12 diseases in open-access papers, as found by Europe PMC text mining. Sharing a sentence is not in itself a finding about the gene and the disease. The quoted sentences say what the papers report.
colon adenocarcinoma (1 paper, 2022). "Promoter methylation levels of 313 colon adenocarcinoma samples and 37 normal tissue samples were analyzed from the TCGA database using the UALCAN platform, indicating that CSTL1 promoter methylation levels in primary malignancies were lower than normal tissue." (PMID 35928453, 2022).
colon cancer (1 paper, 2022). "The clinical relevance of CSTL1, FJX1, IER5L, and KLHL35 in 521 colon cancer cases was assessed, showing the expression level of CSTL1 mRNA was higher than that in normal tissues, and the expression levels of PD, SD, PR, and CR were higher than those in normal tissues." (PMID 35928453, 2022).
colorectal cancer (1 paper, 2022). A primary or metastatic malignant neoplasm that affects the colon or rectum. "However, according to the hypomethylation of CSTL1 in the tumor, which was contrary to the survival curve, this gene was not considered a biomarker of colorectal cancer liver metastasis." (PMID 35928453, 2022).
lung carcinoma (1 paper, 2021). "The level of CEACAM5 (P < 0.001), CNGB1 (P = 0.001), CSTL1 (P = 0.009), RASAL1 (P < 0.001) expression were higher in lung tissues of patients with lung cancer alone than controls." (PMID 33791201, 2021). "The level of CEACAM5 (P < 0.001), CNGB1 (P < 0.001), CSTL1 (P < 0.001), RASAL1 (P < 0.001), SLC4A3 (P < 0.001) expression were also increased in lung tissues of patients with lung cancer coexisting COPD compared to controls." (PMID 33791201, 2021). "In addition, the level of CEACAM5 (P = 0.030), CNGB1 (P = 0.042), CSTL1 (P = 0.046), RASAL1 (P = 0.039), SLC4A3 (P = 0.035) expression were higher in patients with lung cancer coexisting COPD than that in patients with lung cancer alone." (PMID 33791201, 2021).
male infertility (1 paper, 2024). The inability of the male to effect fertilization of an ovum after a specified period of unprotected intercourse. "Mice lacking 8 cystatin genes (Cstl1, Cst11, Cstdc1, Cst12, Cst8, Cst13, Cst9, and Cstdc2) on chromosome 2 possess defective sperm maturation and male infertility." (PMID 38169386, 2024).
mesothelioma (1 paper, 2020). A usually malignant and aggressive neoplasm of the mesothelium which is often associated with exposure to asbestos. "All the proteins of the matrisome-specific interactome of the LOX family expressed in ovarian cancer were also expressed in mesothelioma, except cystatin-like 1 (CSTL1), THSD4 (ADAMTSL-6), and chorionic somatomammotropin hormone 1 (CSH1), which were expressed only in ovarian cancer." (PMID 33383846, 2020).
Obesity (1 paper, 2015). Accumulation of substantial excess body fat. "This raises the question as to which of the remaining 7/11 genes (LBP, RXRB, CPLX1, GLAK2, CSTL1, SLC9A3, CA12) may also have a role in obesity." (PMID 25651499, 2015).
tumor (1 paper, 2022). "The Mann-Whitney U test (Wilcoxon rank-sum test) for unpaired samples showed the expression of CSTL1, FJX1, IER5L, and KLHL35 in tumor tissue was higher than that in normal tissue." (PMID 35928453, 2022).
CSTL1 also shares sentences with these, for which no sentence is quoted: cancer (2 papers); metastasis (1); metastatic cancers (1); ovarian carcinoma (1).